PHIP (PHIP subunit of CUL4-Ring ligase complex)
Diseases named in the same sentence as PHIP in open-access papers (continued):
Sharing a sentence is not in itself a finding about the gene and the disease.
breast carcinoma (6 papers, 2012 to 2022). "The results were consistent with our previous findings in familial breast cancer and supported a breast cancer susceptibility locus at 6q14.1 around the PHIP gene." (PMID 29262523, 2017). "We have used several strategies to study a small region on chromosome 6q14 and found support for a breast cancer susceptibility locus, related to the PHIP gene, with low and moderate risk profiles." (PMID 29262523, 2017). "PAs such as PhIP can increase the risk of breast cancers by binding to and activating ERα, and the PhIP metabolites N2-OH-PhIP, MeIQx, and IFP inhibit the activation of ERα." (PMID 22567014, 2012). "The estrogenic behavior of PhIP has been shown to increase the invasiveness of breast cancer cells but the role of ER in the genotoxicity and metabolic activation of PhIP has not been explored." (PMID 29362861, 2018). "Treatment of MCF-7 breast cancer cells with PhIP and these metabolites significantly inhibits ERα transcription activity at a much lower level than treating with PhIP alone." (PMID 22567014, 2012). "PhIP appears to bind, specifically albeit at a lower affinity than E2, to the ERα-ligand binding domain and, therefore, competes with E2 at its binding site, thereby suggesting an epigenetic mechanism for PhIP, akin to that of E2, in breast cancers." (PMID 22567014, 2012). "PHIP is regarded as an important biomarker for cutaneous melanoma and breast cancer." (PMID 36276071, 2022). "Meanwhile, one of the carcinogenic mechanisms of PhIP is that it may interact with the estrogen receptor and thus promote breast cancer." (PMID 34946837, 2021). "Following ethanol or PhIP treatment of human mammary cells, an increase in intracellular ROS levels was observed that was dependent on a functional ER-α; this is in agreement with published observations using the breast carcinoma cell line MCF-10A." (PMID 29362861, 2018). "Our data show that PhIP can regulate CYP2E1-mediated oxidative stress, and the question arises whether these cellular affects could play a role in the initiation or progression of PhIP-induced mammary cancer." (PMID 29362861, 2018). "This suggests that dietary constituents have both activating and inhibiting effects on hormone-sensitive tissues such as some breast cancers and the risks and development of breast cancers may result either from a defect in the mechanisms for metabolizing PhIP or from overload of PhIP." (PMID 22567014, 2012). "The present study presents a novel mechanism by which the dietary carcinogen PhIP can upregulate CYP2E1 expression, which consequently promotes oxidative stress in breast carcinoma cells." (PMID 29362861, 2018). "We also found that many proteins in the network took part in tumor development; for example, PHIP drives glioblastoma motility and invasion, HDAC2 regulates breast cancer progression and proliferation, and ZFN292 participates in hepatoma proliferation and vasculogenic mimicry." (PMID 34649520, 2021).
diabetes (4 papers, 2016 to 2023). "Expression of transcription factors (ANGPTL2, HP, LEP, SAA1, SAA2), genes related to inflammation (SAA1, LEP), diabetes (IGFBP5) and cancer risk (SAA2) were also elevated upon exposure to 5 nM PhIP.." (PMID 27547236, 2016). "However, we did find that PhIP induces changes in gene expression in various genes that are related to inflammation (SAA1, LEP), diabetes (IBP5) and cancer risk (SAA2)." (PMID 27547236, 2016). "Among the four genes (PHIP, TRPM3, SPTY2D1 and TSPO) associated with fasting insulin and combined into a genetic risk score, we showed that carriers of insulin increasing risk alleles had higher odds of developing diabetes and impaired fasting glucose at follow-up." (PMID 35665752, 2022).
prostate tumor (4 papers, 2011 to 2021). "They showed that grilled meat consumption was associated with increased PhIP-DNA adduct levels in prostate tumor cells, with red meats and hamburgers displaying the most significant association." (PMID 22132129, 2011). "PhIP induces prostate tumors in the F344 rat and CYP1A-humanized (h-CYP1A) C57BL/6 mice but not in wild-type mice, signifying a critical role for human CYP1A2 in PhIP metabolism and tumorigenesis." (PMID 34271992, 2021). "PhIP has been shown to induce prostate tumors in rodent models." (PMID 26689289, 2015).
adenoma (3 papers, 2012 to 2015). A neoplasm arising from the epithelium. "Adenomas were also observed in the colon of PhIP-alone (14.3%) and tomato + broccoli + PhIP-treated animals (12.5%)." (PMID 24312188, 2013). "Thereby, food carcinogens, including PhIP, could accumulate in adenomas and thus promote carcinogenesis." (PMID 25793771, 2015). "Histological analysis demonstrated that PhIP and DSS induced hyperplasia of focal colonic crypt, adenomas and adenocarcinomas in the mucosa layer of the colon with some residual parts of normal colonic architecture." (PMID 23118901, 2012).
Anxiety (3 papers, 2016 to 2025). Intense feelings of nervousness, tension, or panic often arise in response to interpersonal stresses. "Our findings indicate that the PHIP mutation is primarily responsible for core psychological and behavioral symptoms, such as anxiety and depression, while the CLCN4 mutation, by causing brain atrophy, exacerbated the severity of the disorder." (PMID 41383545, 2025). "The PHIP mutation contributed primarily to anxiety and depression, with independent effects on brain structure and cognitive function." (PMID 41383545, 2025). "The PHIP mutation was associated with core neuropsychiatric symptoms, including anxiety and depression, whereas the CLCN4 mutation contributed to severe brain atrophy observed in neuroimaging, further exacerbating cognitive and behavioral deficits." (PMID 41383545, 2025). "Psychological and psychiatric symptoms—including severe anxiety, depression, and other neuropsychological issues—are key features of CJS, typically attributed to PHIP mutations, which regulate neuronal and synaptic growth." (PMID 41383545, 2025).
colorectal cancer (3 papers, 2013 to 2024). A primary or metastatic malignant neoplasm that affects the colon or rectum. "Because of their genotoxic effects observed on heterozygous Apc mutated cells and their possible combined genotoxic effects, both B(a)P and PhIP, taken together, could be implicated in the observed association between meat consumption and colorectal cancer." (PMID 23484039, 2013). "Blocking DNMT3B leads to reduced methylation of the E3 ligase PhIP promoter, which increases PhIP transcription, promotes CDK2 ubiquitination and degradation, and finally leads to the growth arrest of colorectal cancer cells in the G0/G1 phase." (PMID 39228402, 2024).
small intestinal tumors (3 papers, 2013 to 2015). "F1 ob/ob (homozygous mutated) mice had increased body weight (bw) and number of spontaneous and PhIP-induced small intestinal tumors (in ApcMin/+ mice), versus ob/wt (heterozygous mutated) and wt/wt mice (homozygous wild-type)." (PMID 26347815, 2015). "PhIP increased the number of small intestinal tumors compared with the vehicle 0.9% NaCl, in all mice (P < 0.001), in mice given a 10% fat diet (P < 0.001) and a 45% fat diet (P < 0.001)." (PMID 26347815, 2015). "PhIP increased the number of small intestinal tumors in ob/ob mice (P < 0.001), in ob/wt mice (P < 0.001) and in wt/wt mice (P < 0.001), and in both females (P < 0.001, for all three comparisons) and males (P < 0.001, for all three comparisons) of each ob genotype." (PMID 26347815, 2015). "The 45% fat diet increased the number of small intestinal tumors compared with the 10% fat diet, in all mice (P < 0.001), in vehicle-treated mice (P < 0.001), but not in PhIP-treated mice." (PMID 26347815, 2015).
autism (2 papers, 2018 to 2020). Persistent deficits in social interaction and communication and interaction as well as a markedly restricted repertoire of activity and interest as well as repetitive patterns of behavior. "PHIP variants have been identified in individuals with autism." (PMID 29904178, 2018). "Genes located in proximal 6q that have been linked to autism are RIMS1 (regulating synaptic membrane exocytosis 1, MIM*606629), PHIP, SYNCRIP and ZNF292 (zinc finger protein 292, MIM*616213)." (PMID 29904178, 2018).
autism spectrum disorder (2 papers, 2018 to 2024). A spectrum of developmental disorders that includes autism, and Asperger syndrome. "Also, CUL3 and PHIP are both genes known to be involved in autism spectrum disorders." (PMID 39501558, 2024). "However, in our cohort, only 3/14 individuals with a PHIP deletion had an autism spectrum disorder." (PMID 29904178, 2018). "Remarkably, we observed an autism spectrum disorder in 7/13 individuals with an HTR1E and a SYNCRIP deletion, while the numbers were 3/13 for RIMS1, 3/12 for HTR1B, 3/14 for PHIP and 4/10 for ZNF929." (PMID 29904178, 2018).
epilepsy (2 papers, 2020 to 2024). A brain disorder characterized by episodes of abnormally increased neuronal discharge resulting in transient episodes of sensory or motor neurological dysfunction, or psychic dysfunction. "The PHIP gene may become a candidate gene for epilepsy in the future." (PMID 39850204, 2024). "Additionally, four of the brain-expressed, constrained genes that we identified through the new paralog conservation test and presented in the first pre-print version of the manuscript, CHD3, CACNA1E, PHIP, and GABRB2, were recently shown to be significantly enriched in NDDs with epilepsy." (PMID 32183904, 2020).
intestinal tumor (2 papers, 2015 to 2019). "IPA analysis of 270 mutated genes shared by DMBA, MUN, and PhIP treatment with PP2A deficiency in Lgr5+ cells revealed 10 top significantly enriched pathways, including the intestinal tumor metastasis signaling (p-value = 2.12 × 10−57) and Wnt/beta-catenin signaling (p-value = 1.40 × 10−55)." (PMID 31905853, 2019).
lymphoid cancers (2 papers, 2016 to 2020). "On the other hand, female CDF1 mice were more susceptible than male mice to lymphomas and hepatocarcinogenesis induced by chronic PhIP exposure." (PMID 32927802, 2020). "Interestingly, perusal of the Catalogue of Somatic Mutations in Cancer (COSMIC) database revealed that PHIP and SP3 are found mutated in other human cancers, including a small fraction of hematopoietic and lymphoid cancers." (PMID 27982060, 2016).
renal cell carcinoma (2 papers, 2019 to 2022). "In summary, this study firstly demonstrated that PhIP is a risk factor to induce osteoclastogenic activity and metastatic potential in human 786-O renal cell carcinoma cell line, while 6-Shogaol treatment reverses the PhIP-induced effect." (PMID 31569368, 2019). "Human 786-O renal cell carcinoma cells upon induction by PhIP showed increased secretion of both parathyroid hormone-related protein (PTHrP) and IL-8." (PMID 35585878, 2022). "PhIP induced PTHrP and IL-8 secretion in human 786-O renal cell carcinoma cells, which decreased by 2 μM 6-shogaol treatment." (PMID 31569368, 2019). "In summary, this is the first study to demonstrate that PhIP pre-treatment increases the stimulatory effect of human renal cell carcinoma 786-O on osteoclastogenesis activity directly by PTHrP." (PMID 31569368, 2019). "The effect of PhIP on renal cell carcinoma-mediated osteoclastogenesis on CD14+ monocyte-differentiated osteoclasts was further assessed." (PMID 31569368, 2019). "The present study shows that PhIP pre-treatment up-regulates the PTHrP expression in renal cell carcinoma 786-O." (PMID 31569368, 2019). "Our data revealed that PhIP pre-treatment increased the production of parathyroid hormone-related protein (PTHrP) in human 786-O renal cell carcinoma cells." (PMID 31569368, 2019). "Moreover, 6-shogaol also decreases the PhIP-786-O-CM-induced RANKL expression in osteoblasts, suggesting that 6-shogaol might be a potential agent for preventing the aggravating effect of PhIP on renal cell carcinoma bone metastasis." (PMID 31569368, 2019).
autoimmune disease (1 paper, 2024). A disorder resulting from loss of function or tissue destruction of an organ or multiple organs, arising from humoral or cellular immune responses of the individual to their own tissue constituents. "Furthermore, PhIP-Seq has greatly contributed to our understanding of the mechanisms underlying autoimmune diseases and some neurological diseases (Prüss, 2021)." (PMID 39295784, 2024).
breast tumors (1 paper, 2023). "CFA-P may retard the development of PhIP-induced breast tumors, inhibit the formation of PhIP-DNA adducts, and reduce breast carcinogenesis in the context of post-initiation inhibition of cell proliferation." (PMID 37570851, 2023).
Ectrodactyly (1 paper, 2024). A condition in which middle parts of the hands and/or feet (digits and meta-carpals and -tarsals) are missing giving a cleft appearance. "Interestingly, PHIP and UBA2, which have been associated with similar disease profiles of oligodactyly and ectrodactyly, respectively, also showed similar temporal expression patterns in mesenchymal-chondrocytes, -fibroblasts, ectodermal-sost, and muscle cells." (PMID 38228144, 2024).
lupus (1 paper, 2023). "PhIP-seq also identified 14 E3 ubiquitin ligases or E3 ubiquitin complex proteins and 50 additional proteins related to apoptosis, which is notable given evidence of impaired clearance of apoptotic debris in lupus patients." (PMID 37934865, 2023).
medulloblastoma (1 paper, 2022). A malignant, invasive embryonal neoplasm arising from the cerebellum. "Another gene named PHIP was found to be related to glial oncogenesis 36, and was considered as possible tumor suppressor in a murine medulloblastoma model." (PMID 35280693, 2022).
renal agenesis (1 paper, 2024). Renal agenesis (RA) is a form of renal tract malformation characterized by the complete absence of development of one or both kidneys (unilateral RA or bilateral RA respectively), accompanied by absent ureter(s). "The PHIP variant occurred in an individual with a complex malformation syndrome including renal agenesis, hypoplastic radii, oligodactyly of the hands, and polydactyly of the feet." (PMID 38228144, 2024).
skin tumors (1 paper, 2013). "In regards to skin tumors, 42.9% of PhIP-alone treated animals developed lesions." (PMID 24312188, 2013). "In contrast, control animals and, strikingly, tomato + broccoli + PhIP animals did not develop any skin tumors." (PMID 24312188, 2013).
small intestinal carcinoma (1 paper, 2013). "In the PhIP-alone and tomato + broccoli + PhIP groups there was an incidence rate of 35.7% and 25%, respectively, of invasive small intestinal carcinoma compared to animals on the control diet." (PMID 24312188, 2013).
type 2 diabetes (1 paper, 2022). "A gene-level analysis reported in the Metabolic Diseases Knowledge Portal showed associations at ABCA10 with triglycerides, PHIP with fasting insulinadjBMI and type 2 diabetes, and SPTY2D1 with type 2 diabetes." (PMID 35665752, 2022).
tumor (26 papers, 2011 to 2026). "PhIP contributes to carcinogenesis by causing mutation and inflammation by acting as both an initiator and promoter of the tumor." (PMID 35457645, 2022). "PhIP also induces cellular signaling pathways in human prostate cells at human dietary exposure levels, resulting in increased cell proliferation and cell migration, processes linked to the promotion and progression of neoplasia." (PMID 34271992, 2021). "Similarly, combination of MUN or PhIP treatment with PP2A deficiency in Lgr5+ cells also induced tumor formation in vivo." (PMID 31905853, 2019). "Malignancy type and onset time appear to be highly dependent on the experimental model; however, in all models, spontaneous tumor induction by PhIP alone requires lengthy periods of time, typically between 52–82 weeks." (PMID 37174036, 2023). "Previously in GBM, the pleckstrin homology domain interacting protein (PHIP) was localized in the tumor leading edge and was identified as a key driver of migration, invasion, and angiogenesis." (PMID 35877430, 2022). "Both SP3 and PHIP have been reported to exhibit pro-oncogenic activity in some contexts (see Discussion) and yet, in the Eμ-Myc model we clearly identified these as tumor suppressors." (PMID 27982060, 2016). "This distribution of tumors was observed both in 0.9% NaCl-treated and PhIP-treated mice, and after both treatments the tumor numbers were higher in this area with a 45% fat diet compared with a 10% fat diet." (PMID 26347815, 2015). "This is difficult to interpret since PhIP itself decreased the body weight evaluated with all three body weight parameters, probably because of the increased tumor burden." (PMID 25874125, 2015). "GLT treatment significantly suppressed focal hyperplasia, aberrant crypt foci (ACF) formation and tumor formation in mice exposed to PhIP/DSS." (PMID 23118901, 2012). "This activation further stimulated PhIP through an oxidation process, which could trigger or sustain tumor growth." (PMID 37914956, 2024). "PHIP suppression can significantly inhibit tumor cell invasion and progression." (PMID 34298819, 2021). "The bromodomain of PHIP binds to the histone H4K91ac epigenetic mark providing a functional role for PHIP’s bromodomain and presented it as a drug target with therapeutic potential against these tough-to-treat tumor types that lack specific molecular drivers." (PMID 34298819, 2021). "PhIP is a powerful genotoxicant and mammary carcinogen and ROS is genotoxic and tumour promoting." (PMID 29362861, 2018). "As the stimulation of this pathway is associated with the promotion and progression of neoplastic processes, these results suggested that PhIP may be a tumor initiator and promoter of prostate carcinogenesis." (PMID 26689289, 2015). "Additionally, to stimulate tumor growth, PhIP can be used alone or in conjunction with AOM and DMH." (PMID 37174036, 2023). "Thus, PhIP may act as a tumor-initiator and promoter in the prostate and possibly other cancer target organs." (PMID 34271992, 2021). "In the Eμ-Myc model, PHIP and SP3 demonstrated clear in vivo tumor suppressor activity." (PMID 27982060, 2016). "A 45% fat diet exacerbated bw and spontaneous tumor numbers versus 10% fat, but not PhIP-induced tumors." (PMID 26347815, 2015). "In addition to its tumor-initiating activity, PhIP may act via non-genotoxic mechanisms, possibly through the AR, leading to cell proliferation, inflammation, and PC development." (PMID 34271992, 2021).